GABARAPL2 (GABA type A receptor associated protein like 2)
Description:
Ubiquitin-like modifier involved in intra-Golgi traffic (By similarity). Modulates intra-Golgi transport through coupling between NSF activity and SNAREs activation (By similarity). It first stimulates the ATPase activity of NSF which in turn stimulates the association with GOSR1 (By similarity). Involved in autophagy. Plays a role in mitophagy which contributes to regulate mitochondrial quantity and quality by eliminating the mitochondria to a basal level to fulfill cellular energy requirements and preventing excess ROS production. Whereas LC3s are involved in elongation of the phagophore membrane, the GABARAP/GATE-16 subfamily is essential for a later stage in autophagosome maturation.
Synonyms: GEF-2; GATE-16; GEF2; ATG8; GATE16; ATG8C
Tractability: PROTAC: ubiquitination databases record sites on it; its protein half-life has been measured.
Gene: Protein-coding gene on chromosome 16 (75,566,375 to 75,577,881, forward strand). Ensembl gene ENSG00000034713.
Subcellular location: Cytoplasmic vesicle, autophagosome; Endoplasmic reticulum membrane; Golgi apparatus
Subcellular location (Human Protein Atlas): Cytosol; Nucleoplasm; Nuclear bodies
Pathways (Reactome):
Autophagy: Macroautophagy
Vesicle-mediated transport: TBC/RABGAPs
Gene Ontology:
Molecular function: phosphatidylethanolamine binding; protein binding; ubiquitin protein ligase binding; ATPase binding; beta-tubulin binding; GABA receptor binding; microtubule binding; SNARE binding; phospholipid binding
Biological process: autophagosome assembly; negative regulation of proteasomal protein catabolic process; protein localization to endoplasmic reticulum; autophagosome maturation; autophagy; cellular response to nitrogen starvation; intra-Golgi vesicle-mediated transport; mitophagy; positive regulation of ATP-dependent activity
Cellular component: autophagosome; autophagosome membrane; cytoplasm; endoplasmic reticulum membrane; Golgi membrane; cytosol; Golgi apparatus
Genetic constraint (gnomAD): Loss-of-function variants: 8 observed, 8.96 expected, observed/expected ratio (o/e) 0.89, 90% interval 0.52 to 1.58. That is too few expected variants to judge how well the gene tolerates losing a copy. Missense variants: 56 observed, 66.53 expected, observed/expected ratio (o/e) 0.84, 90% interval 0.68 to 1.05. Synonymous variants: 26 observed, 23.86 expected, observed/expected ratio (o/e) 1.09, 90% interval 0.8 to 1.51.
Homologues: Orthologues: chimpanzee GABARAPL2 (100% identical), dog GABARAPL2 (100% identical), guinea pig GABARAPL2 (100% identical), macaque GABARAPL2 (100% identical), mouse Gabarapl2 (100% identical), rabbit GABARAPL2 (100% identical), rat Gabarapl3 (100% identical), zebrafish gabarapl2 (97% identical), tropical clawed frog gabarapl2 (93% identical), pig GABARAPL2 (82% identical), Caenorhabditis elegans lgg-2 (38% identical). Paralogues in human: GABARAPL1 (61% identical), GABARAP (58% identical), MAP1LC3A (43% identical), MAP1LC3C (43% identical), MAP1LC3B (40% identical), MAP1LC3B2 (39% identical).
Diseases named in the same sentence as GABARAPL2 in open-access papers:
GABARAPL2 is named in the same sentence as 30 diseases in open-access papers, as found by Europe PMC text mining. Sharing a sentence is not in itself a finding about the gene and the disease. The quoted sentences say what the papers report.
vitiligo (3 papers, 2022 to 2024). Generalized well circumscribed patches of leukoderma that are generally distributed over symmetric body locations and is due to autoimmune destruction of melanocytes. "Then, five mitophagy hub genes (GABARAPL2, SP1, USP8, RELA, and TBC1D17) were identified using two machine learning algorithms, and these genes showed high diagnostic specificity for vitiligo." (PMID 37287971, 2023). "Considering the central role of IFN-γ in vitiligo, it is speculated that GABARAPL2 engages in vitiligo by regulating mitophagosome maturation and the IFN-γ-driven immune response." (PMID 37287971, 2023). "Furthermore, GABARAPL2, RELA, TBC1D17, and USP8, except of SP1, are implicated in cellular responses to stress and external stimuli; External stimuli, such as stress and oxidative stress, are vital factors in the etiology of vitiligo." (PMID 37287971, 2023). "The results showed elevated GABARAPL2 and USP8 and decreased RELA, SP1, and TBC1D17 in vitiligo compared to healthy controls, which were consistent with bioinformatic analysis results." (PMID 37287971, 2023). "Consistent with the bioinformatic analysis results, GABARAPL2 and USP8 mRNA levels were raised in vitiligo lesions, whereas the mRNA levels of RELA, TBC1D17, and SP1 were decreased." (PMID 37287971, 2023). "Through LASSO regression analysis and the random forest algorithm, we screened five mitophagy-related hub DEGs (GABARAPL2, USP8, RELA, SP1, and TBC1D17) in vitiligo." (PMID 37287971, 2023).
gastric cancer (2 papers, 2020 to 2022). A primary or metastatic malignant neoplasm involving the stomach. "The risk score was constructed based on 4 genes (GRID2, ATG4D,GABARAPL2, CXCR4), and gastric cancer patients were significantly divided into high-risk and low-risk groups according to overall survival." (PMID 32477008, 2020).
Parkinson disease (2 papers, 2020 to 2024). A progressive degenerative disorder of the central nervous system characterized by loss of dopamine producing neurons in the substantia nigra and the presence of Lewy bodies in the substantia nigra and locus coeruleus. "In addition, GABARAPL2 was also identified to be involved in Parkinson's disease." (PMID 32685442, 2020).
Alzheimer disease (1 paper, 2023). A progressive, neurodegenerative disease characterized by loss of function and death of nerve cells in several areas of the brain leading to loss of cognitive function such as memory and language. "The aim of this study was to further investigate the role of genes identified in our previous studies as relevant for the pathophysiology of Alzheimer’s disease and T2DM comorbidity, namely ATG16L1, ATG16L2, GABARAP, GABARAPL1, GABARAPL2, and SQSTM1." (PMID 36901549, 2023).
head and neck cancer (1 paper, 2025). A primary or metastatic malignant neoplasm affecting the head and neck. "High mRNA expression of GABARAPL2 has been linked to better overall survival in renal cancer but worse overall survival in head and neck cancer." (PMID 40421419, 2025).
medullary carcinoma (1 paper, 2021). "In radiation-induced medullary carcinoma in 4W rats, the expression of Cdkn2a and Cxcr4 increased, whereas that of seven autophagy regulatory genes (Dapk1, Eif2ak3, Gaa, Hgs, Mapkl4, Mapt, and Pim2) and five autophagy machinery components (Atg4b, Atg5, Gabarapl2, Rab24, and Wipi1) decreased." (PMID 34580369, 2021).
Obesity (1 paper, 2022). Accumulation of substantial excess body fat. "Among the genes, GABARAPL2 is associated with total and high‐density lipoprotein–cholesterol, and SETDB1 is an antiadipogenic factor playing a role in obesity." (PMID 35386394, 2022).
prostate carcinoma (1 paper, 2021). A carcinoma that arises from epithelial cells of the prostate gland. "Further multivariate Cox regression analysis was performed to select 6-gene prognostic signature (FADD, GABARAPL2, MYC, RAB24, RUBCN, and NPC1) and calculated the risk score of the prostate cancer patients." (PMID 33402116, 2021).
rheumatoid arthritis (1 paper, 2024). A chronic, systemic autoimmune disorder characterized by inflammation in the synovial membranes and articular surfaces. "For example, GABARAPL2, as a specific protein, is preferentially recognized by autoantibodies from early rheumatoid arthritis patients." (PMID 38680873, 2024).
Sepsis (1 paper, 2023). Sepsis is defined as life-threatening organ dysfunction caused by a dysregulated host response to infection. "However, sepsis cases with increased levels of mRNA of DHCR7, GABARAPL2, MAOA, MPO, PDZD8, and TFRC had worse overall survival." (PMID 38011291, 2023).
viral infection (1 paper, 2022). "To definitively identify the role of GABARAP family members during viral infection, we performed individual silencing of GABARAPL1 or GABARAPL2 in HeLa cells." (PMID 36044516, 2022).
tumor (5 papers, 2015 to 2023). "Our research has shown that GABARAPL2 is the most prominently expressed gene in both normal and tumor tissue." (PMID 30374741, 2018). "In both normal and tumor tissue, the highest levels of gene expression were observed for GABARAPL2, followed by MAP1LC3B and MAP1LC3A, the lowest for MAP1LC3C." (PMID 30374741, 2018). "An inverse correlation (r = −0.57) was also observed between GABARAPL1 mRNA and tumor stage while a very poor correlation was determined between GABARAP or GABARAPL2 expression levels and the tumor grade (respectively r = −0.3 and r = −0.1)." (PMID 26474850, 2015). "While GABARAP and GABARAPL2 expression are also reduced in the tumor samples, this decrease was not significant." (PMID 26474850, 2015).
cancer (4 papers, 2018 to 2022). A tumor composed of atypical neoplastic, often pleomorphic cells that invade other tissues. "The genes involving cell cycle control, DNA replication, apoptosis, senescence and autophagy in cancer pathways including CDK4, E2F1, Bax, CDKN1A, GADD45A, FAS, GABARAPL2, and SQSTM were significantly upregulated." (PMID 34305605, 2021). "In cancer tissue, only the GABARAPL1 mRNA level was shown to be significantly reduced, whereas those of GABARAP and GABARAPL2 were not." (PMID 30374741, 2018).
infection (2 papers, 2017 to 2023). The state of being infected such as from the introduction of a foreign agent such as serum, vaccine, antigenic substance or organism. "Of note, infection by T. gondii significantly inhibited starvation-induced transcription of autophagy-related genes (i.e., ULK1, BECN1, PINK1, GABARAPL2, SQSTM1, and NBR1), as compared to uninfected serum-starved HFF cultures (i.e., “Control”)." (PMID 37387601, 2023).
neurodegenerative disease (1 paper, 2023). A disorder of the central nervous system characterized by gradual and progressive loss of neural tissue and neurologic function. "GABARAPL2 has not been reported in T2DM, but there are many reports about GABARAPL2 in neurodegenerative disease." (PMID 37223013, 2023).
GABARAPL2 also shares sentences with these, for which no sentence is quoted: bipolar disorder (2 papers); schizophrenia (2); acute myeloid leukemia (1); autism spectrum disorder (1); colon cancer (1); dementia with Lewy bodies (1); depression (1); epilepsy (1); HCMV infection (1); Joubert syndrome 20 (1); nematode infection (1); neurodevelopmental disorder (1); postherpetic neuralgia (1); prostate tumor (1); renal carcinoma (1).